CKS1B (CDC28 protein kinase regulatory subunit 1B)
Diseases named in the same sentence as CKS1B in open-access papers (continued):
Sharing a sentence is not in itself a finding about the gene and the disease.
lung cancer (12 papers, 2015 to 2025). A malignant neoplasm involving the lung. "These insights underscore the potential of targeting CKS1B and its associated pathways for therapeutic strategies in lung cancer." (PMID 40165937, 2025). "However, despite these promising findings, further in vivo and in vitro studies are necessary to validate CKS1B's clinical applicability as a diagnostic and therapeutic target for lung cancer." (PMID 40165937, 2025). "Immune infiltration analysis revealed a potential role of CKS1B in modulating the tumor microenvironment, further supporting its relevance in lung cancer progression." (PMID 40165937, 2025). "CKS1B overexpression has been documented in several cancers, including hepatocellular carcinoma, colon cancer, lung cancer, oral squamous cell carcinoma, breast cancer, and retinoblastoma." (PMID 40165937, 2025). "The initiation and development of many malignant tumors are related to the overexpression of CKS1B, such as colon cancer, lung cancer, gastric cancer, and breast cancer." (PMID 36405738, 2022). "High CKS1B expression has been shown in many cancers, such as hepatocellular carcinoma, colon cancer, lung cancer, oral squamous cell carcinoma, breast cancer, and retinoblastoma (RB), among others." (PMID 33102238, 2020). "CKS1B is a lung cancer-related gene, knockdown of which results in a significant decrease in lung cancer cell proliferation, invasion and migration." (PMID 31992202, 2020). "In H358 CKS1b-OE cells and relapsed lung cancer, PU-H71 has antitumor activity alone or in combination with CDDP or DOX, which it achieves by inhibiting Hsp90." (PMID 33102238, 2020). "Our data demonstrated that miR-197 regulates lung cancer drug resistance and tumor progression by directly targeting the cyclin-dependent kinase CKS1B as well as by indirectly targeting the transcription factor STAT3." (PMID 25597412, 2015). "Remarkably, we observed that siRNA-mediated knockdown of CKS1B resulted in a significant decrease in cell proliferation, invasion, and migration and sensitized the response of three lung cancer cell lines to CDDP and TXL." (PMID 25597412, 2015). "Inhibition of CKS1B expression by pre-miR-197 was confirmed, and the transient transfection of LNA-miR-197 significantly increased CKS1B expression in three lung cancer cell lines by qRT-PCR." (PMID 25597412, 2015). "Moreover, we explored the functional network of CKS1B and its neighboring genes in lung cancer, highlighting significant interactions that include co-localization, pathways, and genetic interactions." (PMID 40165937, 2025). "This suggests elevated CKS1B expression in lung cancer cells." (PMID 40165937, 2025). "Additionally, gene interaction networks were analyzed to assess the functional significance of CKS1B in lung cancer progression." (PMID 40165937, 2025). "Additionally, it was also found that 3-O-(Z)-coumaroyloleanolic acid, a candidate compound for targeting CKS1B, can reverse CKS1B-induced chemoresistance in lung cancer." (PMID 36405738, 2022). "In addition, the expression of CDC28 protein kinase regulatory subunit 1 (CKS1B) in lung cancer cells developed the chemoresistance through the Hsp90 and MEK1/2 pathway." (PMID 35097114, 2022). "Previous studies have reported that high expression of CKS1B could induce drug resistance of lung cancer cells to cisplatin and adriamycin, but it is unclear whether CAFs are involved." (PMID 34845438, 2021). "It was also found that CKS1B could induce chemoresistance in lung cancer which could be reversed by 3‐O‐(Z)‐coumaroyloleanolic acid." (PMID 32960462, 2021). "Kaplan-Meier estimates of event-free survival, metastasis-free survival, and overall survival found that recurrent primary human (RPH) lung cancer patients with CKS1B overexpression showed decreased survival compared to that of incipient primary human (IPH) lung cancer patients." (PMID 33102238, 2020).
lung cancer (continued). "Although we are temporarily unable to provide more specific data on CKS1B and CAFs in the LUAD research, we believe that the results of this paper can provide a new idea for future research on CKS1B and lung cancer drug resistance to a certain extent." (PMID 34845438, 2021). "Another study also showed that PD-L1 expression may be enhanced by CKS1B/STAT3 axis, further promoting lung cancer development." (PMID 36405738, 2022). "On the other hand, although miR-197 has been reported to modulate CKS1B expression in nonsmall cell lung cancer, it did not affect CKS1B expression in CRC." (PMID 31717435, 2019). "The total frequency of CKS1B genetic alteration in patients with 33 tumor types was 3.54% (388/10953), and the top five tumors with the highest frequency were CHOL (cholangiocarcinoma) (16.67%), LIHC (11.56%), BRCA (9.5%), nonsmall cell lung cancer (9.19%), and UCEC (8.77%)." (PMID 34845438, 2021).
colorectal cancer (8 papers, 2018 to 2024). A primary or metastatic malignant neoplasm that affects the colon or rectum. "Increasing evidence has demonstrated that increased expression of cyclin-dependent kinase regulatory subunit 1B (CKS1B) is associated with the pathogenesis of many human cancers, including colorectal cancer (CRC)." (PMID 31717435, 2019). "It was reported that CKS1B expression could be suppressed by miR-1258, inhibiting colorectal cancer proliferation and migration." (PMID 36405738, 2022). "Besides, CKS1B was also found to be upregulated in patients with prostate cancer, colorectal cancer, leukemia, retinoblastoma, and other malignant diseases or animal models." (PMID 34845438, 2021).
gastric cancer (7 papers, 2017 to 2025). A primary or metastatic malignant neoplasm involving the stomach. "Previously, other groups identified that miR-197 and/or miR-204 negatively regulated CKS1B expression in non-small cell lung cancer and gastric cancer, respectively." (PMID 31717435, 2019). "Studies have shown that miR-204 can down-regulate the expression of CKS1B in gastric cancer." (PMID 36405738, 2022). "In addition, miR-204 has also been found to inhibit the proliferation of gastric cancer cells by targeting CKS1B, CXCL1, and GPRC5a." (PMID 34950208, 2021). "For the first time, we identified that CKS1B, CXCL1, and GPRC5A are putative targets of miR-204 and elucidated that miR-204 acted as potential tumor suppressor and, therefore, are useful as a promising therapeutic target for gastric cancer." (PMID 29283424, 2017).
retinoblastoma (7 papers, 2020 to 2024). A malignant tumor that originates in the nuclear layer of the retina. "CDC28 Protein Kinase Regulatory Subunit 1B (CKS1B) represented a potential research target for therapeutics of retinoblastoma." (PMID 32899915, 2020). "Besides, silencing CKS1B could limit the capacity of retinoblastoma (RB) cells proliferation, and migration, as well as angiogenesis by inhibiting MEK/ERK activation." (PMID 36405738, 2022).
non-small cell lung carcinoma (6 papers, 2015 to 2021). A group of at least three distinct histological types of lung cancer, including non-small cell squamous cell carcinoma, adenocarcinoma, and large cell carcinoma. "It was previously demonstrated by members of our laboratory that PD-L1 is controlled by the miR-197/STAT3/CKS1B network in non-small-cell lung cancer." (PMID 33467725, 2021).
pancreatic cancer (6 papers, 2019 to 2025). "In view of the important role of CKS1B in pancreatic cancer immunotherapy, we further explored the association between CKS1B and PD-L1 and its possible regulatory mechanism in pancreatic cancer cell lines." (PMID 36405738, 2022). "Then, further analysis showed that CKS1B was significantly associated with immune infiltration and could predict the immunotherapy effect for pancreatic cancer." (PMID 36405738, 2022). "The association of CKS1B with immune infiltration and immune checkpoint may provide a new direction for immunotherapy of pancreatic cancer." (PMID 36405738, 2022). "Moreover, immune infiltration analysis revealed that CKS1B expression was significantly associated with the level of immune cell infiltration in pancreatic cancer, and knockdown experiments showed a strong correlation between CKS1B and the cell activity and invasiveness of pancreatic cancer." (PMID 39046884, 2024). "Furthermore, CKS1B was substantially linked to histological grading in pancreatic cancer." (PMID 36405738, 2022). "Analysis of 12 pancreatic cancer cell lines revealed a generally elevated CKS1B expression compared to normal human pancreatic duct epithelial (HPDE) cells." (PMID 39897042, 2025). "Collectively, our data demonstrate that overexpression of CKS1B significantly increases the frequency of CSCs in pancreatic cancer cells." (PMID 39897042, 2025). "This paradox prompted further investigation into the impact of CKS1B expression on chemotherapy sensitivity in pancreatic cancer." (PMID 39897042, 2025). "Our findings further elucidate the mechanism of gemcitabine resistance in pancreatic cancer, demonstrating that CKS1B functions as a key gene in mediating resistance to gemcitabine." (PMID 39897042, 2025). "MiR-520h overexpression hampers pancreatic cancer cell migration and invasion and is targeted by LINC00657 to modulate CKS1B in pancreatic cancer cells." (PMID 38394156, 2024). "Li and colleagues found that CKS1B expression in pancreatic tumour tissues was higher than in normal tissues, and this result was validated by reverse transcription‐quantitative polymerase chain reaction." (PMID 39046884, 2024). "A considerably elevated expression level of CKS1B mRNA was found in cancer tissues, including pancreatic cancer tissues." (PMID 36405738, 2022). "Subsequently, the genetic alteration in CKS1B was studied in 149 pancreatic cancer samples (TCGA, Firehose Legacy)." (PMID 36405738, 2022). "Result illustrated that the CKS1B mRNA expression remarkably upregulated in pancreatic cancer cell lines in comparison to HPDE6-C7." (PMID 36405738, 2022). "Next, with the TISIDB website, the role of CKS1B expression in pancreatic cancer subtypes was explored." (PMID 36405738, 2022). "The level of CKS1B expression was further validated using the Oncomine and GEO database, these findings illustrated that CKS1B was overexpressed in pancreatic cancer." (PMID 36405738, 2022). "Transwell migration assays and wound healing assays were performed to assess the effect of CKS1B on the migratory capacity of pancreatic cancer cells." (PMID 36405738, 2022). "Next, we developed a nomogram using age, grade, and CKS1B expression levels to anticipate 1-, 3-, and 5-year survival in pancreatic cancer patients." (PMID 36405738, 2022). "Together, these data indicate that CKS1B serves as an important biomarker for pancreatic cancer patients in predicting their overall survival." (PMID 36405738, 2022). "In conclusion, our research further demonstrates the role of CKS1B in pancreatic cancer and the signaling pathways involved." (PMID 36405738, 2022). "Results from the Kaplan-Meier survival analysis were consistent with those of the univariate Cox analysis, which illustrated that CKS1B expression is substantially linked to OS and PFS in pancreatic cancer." (PMID 36405738, 2022).
pancreatic cancer (continued). "Results indicated that CKS1B knockdown by short hairpin RNA significantly reduced pancreatic cancer cell viability and invasion via regulating PD-L1 expression." (PMID 36405738, 2022). "According to the results, the CKS1B expression level was remarkably elevated in pancreatic cancer tissues." (PMID 36405738, 2022). "Consistent with previous studies, we found that CKS1B was highly expressed in multiple cancers including pancreatic cancer, which was confirmed in the Oncomine and CPTAC databases." (PMID 36405738, 2022). "In conclusion, we first used public databases to examine the differential expression and prognostic significance of CKS1B in pancreatic cancer." (PMID 36405738, 2022). "This study provides further insight into the function and detailed mechanism of CKS1B in pancreatic cancer and suggests that targeting CKS1B is a promising strategy for pancreatic cancer therapy." (PMID 36405738, 2022). "Afterward, we compared the immuneScore and the infiltration levels of immune cells between CKS1B high and low expression groups to examine the involvement of CKS1B in the pancreatic cancer immune microenvironment." (PMID 36405738, 2022). "Our study analyzed the relationship between CKS1B somatic copy number alterations and immune cell infiltration in pancreatic cancer samples using TIMER." (PMID 36405738, 2022). "We undertook KEGG pathway analysis and GSEA to determine the possible cellular processes that CKS1B involved in pancreatic cancer." (PMID 36405738, 2022). "The result showed that CKS1B knockdown cells had significant reductions in LC3-II, which demonstrated that CKS1B was associated with autophagic activity in pancreatic cancer." (PMID 36405738, 2022). "And wound healing assays illustrated that the migratory rate of SW1990 cells with shCKS1B transfection was 13.09 ± 0.37%, lower than that control group 31.32 ± 0.66%, which implied that CKS1B enhanced the migratory capacity of pancreatic cancer cells." (PMID 36405738, 2022). "In our research, CKS1B expression in pancreatic tumor tissue was higher than that in normal tissue by TCGA, Oncomine and CPTAC databases analysis." (PMID 36405738, 2022). "Expression of CKS1B enhanced the stemness properties of pancreatic cancer." (PMID 39897042, 2025). "Additionally, Li and colleagues demonstrated that CKS1B knockdown by short hairpin RNA significantly reduced pancreatic cancer cell viability and invasion through regulation of PD-L1 expression." (PMID 39897042, 2025). "Given this background, it is intriguing to explore whether FOXM1 regulates CKS1B in pancreatic cancer, potentially contributing to the malignant phenotype of PDAC." (PMID 39897042, 2025). "It was found that the CKS1B genetic alteration occurred 4% across 149 pancreatic cancer patients." (PMID 36405738, 2022). "We found that CKS1B was involved in the regulation of autophagy by GSEA analysis, so we further detected whether the autophagy level of pancreatic cancer cells changed after CKS1B knockdown by western blotting." (PMID 36405738, 2022). "Besides, qRT-PCR also substantiated that CKS1B was upregulated in pancreatic cancer cells and tissues." (PMID 36405738, 2022). "In this study, we investigated the expression and prognostic value of CKS1B in pancreatic cancer." (PMID 36405738, 2022). "Furthermore, we demonstrated differential expression of CKS1B in pancreatic cancer cells and tissues using qRT-PCR." (PMID 36405738, 2022). "Additionally, the reverse-phase protein arrays (RPPA) identified the CKS1B protein was frequently expressed in pancreatic cancer tissues." (PMID 36405738, 2022). "In addition, IHC of tissue microarray also showed that CKS1B protein expression is higher in pancreatic cancer tissue." (PMID 36405738, 2022). "Moreover, multivariable regression analysis further supported that CKS1B independently served as a prognostic indicator in pancreatic cancer patients (HR = 1.554, 95% CI = 1.122-2.152, P = 0.008)." (PMID 36405738, 2022).
pancreatic cancer (continued). "We hypothesized that knocking down CKS1B may suppress pancreatic cancer cell viability and migration by blocking PD‐L1 level." (PMID 36405738, 2022). "However, the intrinsic role of CKS1B in pancreatic cancer remains elusive." (PMID 36405738, 2022). "Besides, we further determined the CKS1B expression in pancreatic cancer cell lines." (PMID 36405738, 2022). "The interaction between CKS1B and PKMYT1 can disrupt the G2/M checkpoint, dysregulate the cell cycle, and promote abnormal proliferation in pancreatic cancer." (PMID 40857024, 2025). "Nevertheless, deeper comprehension of the clinical prognosis and mechanistic explanation of CKS1B in pancreatic cancer is lacking." (PMID 36405738, 2022). "Besides, we investigated the possible link between the CKS1B expression and PFS in pancreatic cancer patients." (PMID 36405738, 2022).
liver cancer (4 papers, 2015 to 2022). An epithelial or non-epithelial malignant neoplasm that arises from the liver. "Upregulation of SKP2 and its partner, CDC28 protein kinase regulatory subunit 1B (CKS1B), has been shown to be associated with a dismal prognosis and unconstrained tumor proliferation in liver cancer." (PMID 25537506, 2015). "For example, a similar strategy was successfully employed to identify synthetic dosage lethal interactions with CKS1B, which is frequently amplified in breast, lung, and liver cancers." (PMID 34550356, 2021). "Re-expression of CKS1B overcomes miR-1258 induced apoptosis and increases stemness of HCC cells, suggesting that loss of miR-1258 contributes to carcinogenesis and progression of liver cancer through targeting CKS1B." (PMID 27270326, 2016).
lymphoma (4 papers, 2013 to 2019). A malignant (clonal) proliferation of B- lymphocytes or T- lymphocytes which involves the lymph nodes, bone marrow and/or extranodal sites. "CKS1B is involved in Myc-induced lymphoma in mouse and aggressive mantle cell lymphoma in humans." (PMID 24130802, 2013). "CKS1B is transcriptionally induced by c-MYC and negatively regulates the cyclin-dependent kinase (Cdk) inhibitor p27Kip1 in lymphoma, supporting c-MYC tumorigenesis." (PMID 25477524, 2015).
nasopharyngeal carcinoma (4 papers, 2015 to 2021). A carcinoma arising from the nasopharyngeal epithelium. "The CKS1B gene is located at chromosome 1q21, which is over-represented in hepatocellular, and nasopharyngeal carcinoma." (PMID 29283424, 2017). "Besides, overexpression of CKS1B contributed to poor prognosis of nasopharyngeal carcinoma." (PMID 32960462, 2021).
breast tumors (2 papers, 2016 to 2024). "miRNA inhibition promoted copy gains and increased expression of the drug-resistant oncogene CKS1B, which was further substantiated in primary breast tumors." (PMID 26755726, 2016).
cervical cancer (2 papers, 2015 to 2019). A primary or metastatic malignant neoplasm involving the cervix. "We tested this possibility by focussing our attention on the miR-181c target gene, CKS1B, which belonged to the significantly enriched pathway in cervical cancers." (PMID 30937183, 2019).
gastric adenocarcinoma (2 papers, 2017 to 2021). "CKS1B is also associated with lymph node metastasis and is associated with poor prognosis in gastric adenocarcinoma." (PMID 29283424, 2017).
leukaemia (2 papers, 2018 to 2021). "Furthermore, high levels of CKS1B observed in haematopoietic stem and progenitor cells (CD34+) indicate that CKS1B may be a central factor of the stem cell program hijacked by MLL-FPs in MLLr leukaemia." (PMID 28939057, 2018). "Altogether, these analyses revealed a dysregulation of CKS expression in MLLr leukaemia, but also in BCR-ABL positive CML, consistent with putative roles for CKS1B and CKS2 in leukaemogenesis." (PMID 28939057, 2018). "On the contrary, CKS1B genetic variation was hardly observed in KIRC, leukemia, undifferentiated STAD, seminoma, nonseminomatous germ cell tumors, well-differentiated thyroid carcinoma, and ocular melanoma." (PMID 34845438, 2021).
lymph node metastasis (2 papers, 2017 to 2020). "Importantly, CKS1B upregulation has been positively related to increased proliferation, migration, angiogenesis, invasion and chemoresistance, being further related with lymph node metastasis and worse prognosis." (PMID 32183400, 2020).